MBTPS2 (membrane bound transcription factor peptidase, site 2)
Diseases named in the same sentence as MBTPS2 in open-access papers (continued):
Sharing a sentence is not in itself a finding about the gene and the disease.
osteosarcoma (1 paper, 2022). A usually aggressive malignant bone-forming mesenchymal neoplasm, predominantly affecting adolescents and young adults. "Initially, we detected the mRNA expression levels of two autophagy-associated genes, MYC and MBTPS2, in osteosarcoma patients’ tissues through RT-qPCR." (PMID 36586072, 2022). "It is the first study to point out the association between MBTPS2 and osteosarcoma." (PMID 36586072, 2022). "More importantly, we verified that autophagy-related genes, MYC and MBTPS2, were closely related to tumor cells metastasis in osteosarcoma." (PMID 36586072, 2022). "Our experimental results showed confirmed low-expression levels of MBTPS2 in osteosarcoma and its overexpression attenuated the migration and invasion of MG63 and U2OS cells." (PMID 36586072, 2022). "Conclusively, we confirmed the correlation of MYC or MBTPS2 with autophagy and metastasis in osteosarcoma, which provides further verification of the validity of the model." (PMID 36586072, 2022). "Collectively, these results demonstrated that MYC and MBTPS2 were involved in the metastasis of human osteosarcoma cells by affecting autophagy, which was consistent with our findings based on the public databases." (PMID 36586072, 2022). "In cell experiments, similar results were found that MYC and MBTPS2 were differentially expressed in hFOB and osteosarcoma cell lines at the mRNA and protein levels." (PMID 36586072, 2022). "Since we were more interested in MYC and MBTPS2, we further verified their expression in osteosarcoma and their correlation with osteosarcoma metastasis in vitro." (PMID 36586072, 2022). "MYC knockdown or MBTPS2 overexpression prevented the capacity of migration and invasion in osteosarcoma cell lines through inhibiting cellular autophagy." (PMID 36586072, 2022). "Given the intricate connection between autophagy and metastasis, we next examined the effects of MYC silencing and MBTPS2 overexpression on metastasis ability of osteosarcoma cells by Transwell assay." (PMID 36586072, 2022). "Furthermore, RT-qPCR, Western Blotting and IHC results indicated that MYC and MBTPS2 were differently expressed in osteosarcoma tissues and cell lines." (PMID 36586072, 2022). "Similar results were obtained in osteosarcoma cells with overexpressed MBTPS2." (PMID 36586072, 2022). "Our findings also suggested that MYC and MBTPS2 were two major factors regulating autophagy in osteosarcoma, and could serve as potential therapeutic targets for osteosarcoma." (PMID 36586072, 2022). "Finally, we found that MYC knockdown or MBTPS2 overexpression inhibited osteosarcoma migration/invasion through affecting autophagy." (PMID 36586072, 2022). "However, the role of MBTPS2 in osteosarcoma remains unknown." (PMID 36586072, 2022). "Afterward, we detected the expression levels and effects on osteosarcoma cells metastasis of MYC and MBTPS2, which were involved in the model." (PMID 36586072, 2022). "To further validate the biological functions of MYC and MBTPS2 in osteosarcoma cells, we depleted MYC expression in 143B and HOS cells with siRNA technology, and elevated the expression levels of MBTPS2 in MG63 and U2OS cells by overexpression plasmid." (PMID 36586072, 2022). "Moreover, the results of IHC demonstrated that MYC expression was up-regulated in the metastatic osteosarcoma patient, and MBTPS2 showed relatively high expression level in the non-metastasis patient, which suggested the relationship between autophagy and metastasis in osteosarcoma." (PMID 36586072, 2022). "The results indicated that osteosarcoma samples showed higher MYC mRNA expression levels than that of corresponding adjacent nontumorous tissues, while MBTPS2 expression levels were relatively low in tumor samples." (PMID 36586072, 2022).
prostate tumours (1 paper, 2023). "Transposon insertion sites in tumours from SB:PtenNull mice were identified, and in three mice, we identified a single insertion sites in the Mbtps2 gene, resulting in an increase in transcript levels in their prostate tumours." (PMID 36991255, 2023).
tumor (13 papers, 2017 to 2024). "In the 20 pairs of clinical samples we collected, rt-PCR results showed that ZNF678, ARID1A, XIAP, MIS18BP1, and MBTPS2 were highly expressed in tumor tissues." (PMID 36249009, 2022). "Notably, 8 autophagy-related genes (CAPN10, DAPK2, MBTPS2, ST13, CFLAR, FADD, PEX14 and TSC2) and 2 immune cells (Mast cells and Eosinophils) were revealed to be highly associated with tumor prognosis." (PMID 34093817, 2021). "Nevertheless, our results provide a new insight regarding the expression patterns of Mbtps2 and YY2, especially in tumor." (PMID 28903375, 2017).
cancer (10 papers, 2014 to 2025). A tumor composed of atypical neoplastic, often pleomorphic cells that invade other tissues. "siRNA-mediated gene knockdown of MBTPS2 significantly decreased cell proliferation in all 3 cancer cell lines in growth assay over 120 h." (PMID 36991255, 2023). "Apoptotic cells and changes in lipid synthesis in different pan-cancer cells need to be specifically observed, and more evidence is needed for whether these changes are caused by the inhibition of cell-cycle-related proteins followed by the inhibition of MBTPS2 and SREBF1 expression." (PMID 37958642, 2023). "The cancer cell lines expressed MBTPS2 mRNA at significantly higher levels than RWPE-1 cells (PC3 vs RWPE-1 ~20-fold change; LNCaP vs RWPE-1 10-fold change; and DU145 vs RWPE ~6-fold change)." (PMID 36991255, 2023). "Our DNA-methylation-based predictors selected CpG sites and CGIs related to genes previously found individually involved in cancer development and with transcriptional activity regulated by methylation (e.g. MBTPS2, YY2, ECRG4, IKZF1)." (PMID 31708973, 2019). "RNA-Seq of the MBTPS2 knockdown cell lines demonstrated that changes in lipogenic signalling, and cholesterol metabolism could contribute to the cancer phenotype." (PMID 36991255, 2023).
infection (5 papers, 2014 to 2023). The state of being infected such as from the introduction of a foreign agent such as serum, vaccine, antigenic substance or organism. "Among these, disruption of the canonical SREBP regulators SCAP, MBTPS1, and MBTPS2 conferred resistance to SARS-CoV-2 infection, with a similar effect for infection with the ACE2-independent HCoV-OC43 and HCoV-229E but not the ACE2-dependent HCoV2-NL63." (PMID 35231079, 2022).
genetic disorder (2 papers, 2011 to 2021). "The main limitations of our study arise from the rarity of the genetic disorders caused by MBTPS2 pathogenic variants and the difficulty in obtaining the relevant biological samples for molecular characterization." (PMID 34093655, 2021). "Recently, mutations in the MBTPS2 gene were found in KFSD patients indicating that both IFAP and KFSD are within the spectrum of one genetic disorder with overlapping phenotypes." (PMID 21600032, 2011).
skin disorder (1 paper, 2021). Any deviation from the normal structure or function of the skin or subcutaneous tissue that is manifested by a characteristic set of symptoms and signs. "Any insights gained from these studies will further our understanding of the MBTPS2 properties in disease, and thereby assist in the possibility of utilizing MBTPS2 as a therapeutic target for the treatment of its associated skin disorders and OI." (PMID 33743732, 2021).
MBTPS2 also shares sentences with these, for which no sentence is quoted: alopecia (3 papers); viral infection (3); colorectal cancer (2); COVID-19 (2); Intellectual disability (2); liposarcoma (2); anemia (1); bone disorder (1); bone marrow fibrosis (1); cerebral malaria (1); cervical cancer (1); developmental delay (1); epilepsy (1); genodermatosis (1); glioma (1); growth failure (1); hearing (1); Hyperkeratosis (1); hypertriglyceridemia (1); hypoalphalipoproteinemia (1); hypobetalipoproteinemia (1); ichthyosis vulgaris (1); Inguinal hernia (1); malaria (1); metabolic disorders (1); Nail dystrophy (1); Osteogenesis Imperfecta type XIX (1); Pulmonic stenosis (1); Thrombocytopenia (1).